GPHA2 (glycoprotein hormone subunit alpha 2)
Description:
Functions as a heterodimeric glycoprotein hormone with GPHB5 able to bind and activate the thyroid-stimulating hormone receptor (TSHR), leading to increased cAMP production. Plays a central role in controlling thyroid cell metabolism.
Synonyms: GPA2; ZSIG51; A2; MGC126572
Tractability: Antibody: its Gene Ontology location is reachable by antibodies, with high confidence; UniProt places it where antibodies can reach, with medium confidence; UniProt predicts a signal peptide or a membrane-spanning region.
Gene: Protein-coding gene on chromosome 11 (64,934,471 to 64,935,893, reverse strand). Ensembl gene ENSG00000149735.
Subcellular location: Secreted
Subcellular location (Human Protein Atlas): Vesicles; Predicted to be secreted
Pathways (Reactome):
Signal Transduction: G alpha (s) signalling events; Hormone ligand-binding receptors
Gene Ontology:
Molecular function: protein binding; protein heterodimerization activity; thyrotropin-releasing hormone receptor binding; hormone activity
Biological process: adenylate cyclase-activating G protein-coupled receptor signaling pathway; cell surface receptor signaling pathway
Cellular component: extracellular region
Genetic constraint (gnomAD): Loss-of-function variants: 12 observed, 15.04 expected, observed/expected ratio (o/e) 0.8, 90% interval 0.51 to 1.29. The upper end of that interval is the gene's LOEUF score, 1.29, which puts it in group 5 of 6, group 1 being the genes least tolerant of losing a copy. Missense variants: 156 observed, 172.93 expected, observed/expected ratio (o/e) 0.9, 90% interval 0.79 to 1.03. Synonymous variants: 61 observed, 68.39 expected, observed/expected ratio (o/e) 0.89, 90% interval 0.73 to 1.1.
Homologues: Orthologues: chimpanzee GPHA2 (98% identical), pig GPHA2 (90% identical), rat Gpha2 (85% identical), guinea pig GPHA2 (84% identical), mouse Gpha2 (83% identical), macaque GPHA2 (78% identical), dog GPHA2 (74% identical), tropical clawed frog gpha2 (67% identical), zebrafish gpha2 (55% identical), Drosophila melanogaster Gpa2 (26% identical), Caenorhabditis elegans gpla-1 (23% identical).
Diseases named in the same sentence as GPHA2 in open-access papers:
GPHA2 is named in the same sentence as 14 diseases in open-access papers, as found by Europe PMC text mining. Sharing a sentence is not in itself a finding about the gene and the disease. The quoted sentences say what the papers report.
type 1 diabetes (1 paper, 2024). "Similarly, in mice with type 1 diabetes, the expression of putative LESC markers K15, ∆Np63α, and glycoprotein hormone alpha-2 (GPHA2) was reduced in the limbus." (PMID 38534414, 2024).
tumor (3 papers, 2016 to 2022). "It has been found that GPHB5 and GPHA2 can form a heterodimer (GPHB5/GPHA2) and are secreted into the blood to participate in reproduction, tumor cell proliferation, skeletal development, and immune and inflammatory regulation." (PMID 36568071, 2022).
GPHA2 also shares sentences with these, for which no sentence is quoted: cyst (4 papers); infection (3); cancer (1); Chagas disease (1); glaucoma (1); hypothyroidism (1); metabolic disorders (1); metabolic syndrome (1); nematode infection (1); neuroblastoma (1); Obesity (1); pancreatic cancer (1).